5S_rRNA (5S ribosomal RNA )
Gene: Ribosomal RNA gene on chromosome 6 (15,522,195 to 15,522,300, reverse strand). Ensembl gene ENSG00000277411.
Homologues: Orthologues: mouse Gm54938 (57% identical), chimpanzee 5S_rRNA (55% identical). Paralogues in human: RNA5S1 (53% identical), RNA5S10 (53% identical), RNA5S11 (53% identical), RNA5S12 (53% identical), RNA5S13 (53% identical), RNA5S14 (53% identical), RNA5S15 (53% identical), RNA5S16 (53% identical), RNA5S17 (53% identical), RNA5S2 (53% identical), RNA5S3 (53% identical), RNA5S4 (53% identical), and 26 more.